CTLA4 (cytotoxic T-lymphocyte associated protein 4)
Diseases named in the same sentence as CTLA4 in open-access papers (continued):
Sharing a sentence is not in itself a finding about the gene and the disease.
tumor (continued). "In animal tumor models, nanodiscs cleared tumors when combined with anti-PD-1 and anti-CTLA-4 therapies." (PMID 31779642, 2019). "Some studies have shown that stimulating the ICOS pathway markedly enhances the efficacy of CTLA-4 blockade in cancer immunotherapy, while inhibiting the ICOS pathway reduces the efficacy of anti-CTLA-4 drugs and reduces tumor rejection." (PMID 31195368, 2019). "One approach to improve the response rate and reduce immune-related adverse events of anti-CTLA-4 antibodies is to direct the effect to the tumor using bispecific antibodies (bsAbs)." (PMID 30975201, 2019). "In HNSCC patients, the expression of CTLA-4 in tumor-infiltrated lymphocytes was significantly higher than that in peripheral lymphocytes." (PMID 31708918, 2019). "To investigate this further, we injected anti-CTLA-4 or anti-PD-1 mAb in EG7 tumor-bearing Casp1/11−/− or Nlrp3−/− mice." (PMID 31085177, 2019). "The second study combined tremelimumab with ablation therapy in patients with advanced HCC in order to induce tumor necrosis, thereby promoting the release of tumor antigens to increase the efficacy of anti-CTLA-4." (PMID 31783782, 2019). "Compared with mice receiving monotherapy, administration of BayK8644 in combination with anti-CTLA-4 mAb significantly improved survival of EG7 tumor-bearing mice." (PMID 31085177, 2019). "Cancer treatments with immune checkpoint inhibitors targeting CTLA-4 or the PD-1/PD-L1 axis can prevent dysfunction of tumor-directed CD8 T-cell responses and have shown durable responses in humans with advanced cancers." (PMID 31324774, 2019). "Blockade of the immunosuppressive checkpoint receptors cytotoxic T-lymphocyte-associated protein 4 (CTLA4) or programmed death 1 (PD-1) and its cognate ligand, programmed death 1 ligand (PD-L1), has altered the landscape of anti-tumor immunotherapy." (PMID 30609841, 2019). "A combination of different immune checkpoint inhibitors, such as anti-CTLA-4 plus anti-PD-1, has showed a manageable tolerability profile with anti-tumor activity and clinical benefits." (PMID 31333652, 2019). "The murine sarcoma model showed that mostly mutant neoantigens were responsible for recognizing the tumor during anti- PD-1 and CTLA-4 treatment." (PMID 31709183, 2019). "So, the synergistic anti-tumor effects of Lactobacillus acidophilus lysates combined with CTLA-4-blocking antibodies need to be further confirmed in multiple CRC tumor models." (PMID 31882868, 2019). "PET imaging was performed to examine the biodistribution and pharmacokinetic properties of 64Cu-DOTA-anti-CTLA-4 mAb, and the data showed a significantly higher accumulation in the tumor." (PMID 30506221, 2019). "CTLA-4 and PD-1 are receptors expressed by T-cells that regulate immune responses at the priming phase in lymph nodes and at the effector phase in the tumor, respectively." (PMID 31892230, 2019). "After tumor implantation, mice were dosed twice a week with a combination of α-PDL-1 + α-CTLA-4 or isotype controls for 2 weeks and tumor growth and survival were measured." (PMID 31779705, 2019). "Tumor free-survival after re-challenge was detected in half of the mice treated with combined therapy and in one-third of mice treated with CTLA-4/PD-1 immune checkpoint inhibitors alone." (PMID 31150505, 2019). "B. fragilis was reported to enhance anti-CTLA-4 efficacy via a proposed mechanism involving the activation of Th1 cells with cross-reactivity to bacterial antigens and tumor neoantigens." (PMID 30995949, 2019). "When cryoablation was combined with an immune checkpoint inhibitor, anti-cytotoxic T lymphocyte-associated protein 4 (CTLA-4) antibody, this anti-tumour effect was further enhanced with up to 80% of the mice becoming tumour free." (PMID 31111237, 2019). "Currently, a first clinical CTLA-4 imaging study is ongoing, where tumor lesion uptake and biodistribution of 89Zr-labeled ipilimumab will be assessed at the start of ipilimumab therapy and 3 weeks post start of therapy." (PMID 31696402, 2019).
tumor (continued). "Decisions on which targeted therapies and which immune checkpoint therapies were administered (anti-PD-1 monotherapy vs. combined anti-PD-1 and anti-CTLA-4 therapy) were taken by the multi-disciplinary tumor board." (PMID 31921863, 2019). "It is well known that IO drugs administered as single agents, including CTLA-4, generally are poor at inducing anti-tumor responses in this model." (PMID 30975201, 2019). "The long-term effect of pGP100 DNA vaccine and CTLA-4/PD-1 immune checkpoint blockade on tumor growth and mice survival was followed in naïve and treated mice bearing B16F10 tumors." (PMID 31150505, 2019). "By combining cytotoxic T lymphocyte-associated antigen 4 (CTLA-4) blockade-mediated immunotherapy with CDSDM NR treatment, strong tumor regression was observed." (PMID 34138044, 2019). "With the simultaneous use of anti‐CTLA‐4, about 84% of the treated tumor‐bearing mice achieve long‐term survival and 34% of mice develop tumor‐specific immunity." (PMID 31131193, 2019). "As tumour infiltrating T cells are often anergic and express immune-checkpoints such as PD-1 and CTLA-4, there will be a paucity of T cell-derived IL2 that will impact upon tumour infiltrating NK cells." (PMID 31595191, 2019). "We assessed these aspects of B cell biology in 473 SKCM from the Cancer Genome Atlas Project (TCGA) as well as in RNA-seq data corresponding to tumor samples procured from patients who received CTLA-4 and PD-1 inhibitors for metastatic SKCM." (PMID 31138334, 2019). "In a rat liver transplantation model with tumor recurrence, hepatic expressions of CTLA-4, TGF-β and PD-L1 were increased in the tumor tissues from small-for-size liver graft group compared to whole graft group." (PMID 29843754, 2018). "In the process of tumor progression, the immune activity of T cells is dampened by upregulation of the immune checkpoint molecules such as PD-1/PD-L1 and CTLA-4 in the tumor microenvironment, resulting in tumor immune escape." (PMID 30305604, 2018). "For example, anti-SEMA4D plus anti-CTLA-4 resulted in 90% complete tumor rejection (CR) (p<0.0001) in an HNSCC model representative of a T cell inflamed tumor with high MDSC suppression." (PMID 30400822, 2018). "We recently demonstrated that blockade of either CTLA-4 or PD-1 efficiently inhibited the tumor growth of a murine squamous cell carcinoma (SCC) cell line (SCCVII) in syngeneic mice; however, we failed to eradicate the tumors." (PMID 29568358, 2018). "The dramatic anti-tumor clinical responses observed in certain tumors treated with anti-CTLA-4 and anti-PD-1 antibodies have ushered in a new era for effective cancer therapies." (PMID 30854331, 2018). "Because of the success of tumor immunotherapy, especially immune-checkpoint blockade therapies including anti-PD-1 and anti-CTLA-4 antibodies, immune cells in tumor microenvironment have gained substantial attention in recent years." (PMID 30275936, 2018). "The first preclinical report of CTLA-4 blockade using an anti-CTLA-4 antibody was published by Leach and colleagues in 1996, who showed an enhanced immune response leading to an effective tumor elimination." (PMID 29494517, 2018). "In HCC, the coordinated expression of other immune regulators with PD-L1, PD-1, and CTLA-4 in tumor tissue have been less well-studied." (PMID 30057891, 2018). "Monoclonal antibodies to the CTLA-4 (a protein regulating T cell tolerance) have entered clinical cancer therapy and have been proven highly effective in several types of tumor." (PMID 30249019, 2018). "Some of the receptor/ligand combinations between T-cells and tumor cells are inhibitory in nature such as PD-1/PD-L1 (programmed cell death receptor and ligand) and CTLA-4/B7 (cytotoxic T lymphocyte-antigen 4)." (PMID 29942724, 2018). "For instance, mass cytometry profiling of tumor-infiltrating T cells revealed differences in the T cell phenotypes of patients treated with anti-PD-1 compared to anti-CTLA-4." (PMID 29968076, 2018).
tumor (continued). "CTLA4 blockade by ipilimumab provides suppression of the inhibitory signal to T-cells and increases the chances for activation against tumour cells." (PMID 29642948, 2018). "Dual Tim-3 and PD-1 blockade or even combining anti-Tim-3, anti-PD-1, and anti-CTLA-4 shows synergistic anti-tumor effects in several cancer types, more effective than any monotherapy." (PMID 30309387, 2018). "In further studies, the TCR diversity in peripheral blood of tumor patients treated with anti-CTLA-4 antibodies has been determined." (PMID 29494517, 2018). "Compared with a-CTLA-4, treatment of tumor-bearing mice with a-CTLA4-TGFβRII resulted in a marked decline of FOXP3-expression in CD4+ cells." (PMID 29467463, 2018). "Consistent with the human in vitro data, dexamethasone increased the percentage of CTLA-4-expressing CD4 T cells of tumor-bearing mice in a dose-dependent manner." (PMID 29891009, 2018). "Antibody antagonists against CTLA-4 and PD-1/PD-L1 attenuate tumor-induced inhibitory signaling, thereby shifting towards T-cell stimulation and bolstering adaptive tumor immunity." (PMID 30558196, 2018). "Studies in mouse tumor models showing that CTLA-4 antibodies can function by depleting intratumoral Tregs via Fc-receptor dependent mechanisms have received much attention." (PMID 30233564, 2018). "Our previous work showed that injecting immunotoxins directly into tumors in combination with anti-CTLA-4 antibody had a synergistic anti-tumor effect in the 66C14 murine breast tumor model." (PMID 30441807, 2018). "The analysis of peripheral blood and tumor tissue specimens in patients receiving anti-PD-1, anti-CTLA-4, or the combinatorial therapy demonstrated that CTLA-4 blockade induced a proliferative signature in a subset of memory T cells." (PMID 30519541, 2018). "For example, in mice with melanoma established by subcutaneous injection of B16 cells, an anti-MARCO monoclonal antibody treatment enhances the efficacy of anti-CTLA4 antibody treatment in suppressing tumor growth." (PMID 29670880, 2018). "Another target in antitumor therapy, CTLA-4, which can be expressed on tumor cells, infiltrating Tregs as well as on exhausted conventional T cells, is regarded as an immunosuppressive factor, but its role as a prognostic factor is unclear." (PMID 30413032, 2018). "Cytometric analyses have also shown upregulation of immunotherapeutic targets such as CTLA-4 in tumor infiltrating T-cells, suggesting a possible role of oncolytic viruses in neo-adjuvant/adjuvant treatment along with systemic immunotherapies." (PMID 30514385, 2018). "Antagonist antibodies to CTLA-4 are in clinical trials to evaluate their anti-tumor efficacy alone and in combination with other therapeutic antibodies, including those targeting the PD-1 and PD-L1 signaling axis." (PMID 29617360, 2018). "Administration of the VE800 cocktail with anti-CTLA4 enhanced anti-tumor activity and survival in the MC38 tumor model." (PMID 30400822, 2018). "Our findings show that CTLA-4 inhibition in the context of whole cell vaccination induced activation and expansion of TILs that were partially effective in controlling tumor growth." (PMID 29377881, 2018). "Potentially, tumor expression of CTLA-4 and PD-L1 can provide a rationale for screening of the tumor samples to identify candidates for the targeted therapies and further provide rationales for investigation of the anti-immune checkpoint treatments." (PMID 29672601, 2018). "While cancer immunotherapies directed against PD-1 and CTLA-4 are showing unprecedented efficacy, some patients and tumor types remain refractory to these therapies." (PMID 30400822, 2018). "At present, the checkpoint inhibitor anti-cytotoxic T-lymphocyte-associated protein 4 (anti-CTLA-4) and anti-programmed death-1 (anti-PD-1) are representative of the tumor immunotherapy program and have been widely studied." (PMID 29958545, 2018).
tumor (continued). "IL-2/CD40 reduced CD25 and IFN-γ in tumor-associated CD4+ T cells in both age groups alongside reductions in the regulatory markers CD73 and CTLA-4." (PMID 30560130, 2018). "Vehicle or dexamethasone treatment was initiated on day 7, and isotype or CTLA-4 blocking antibody were administered on days 13, 16, and 19 following tumor implantation." (PMID 29891009, 2018). "In clinical practice and in many clinical trials, anti-CTLA-4 immunotherapies, such as ipilimumab and tremelimumab, are used in many tumor models." (PMID 30487462, 2018). "This allows ATOR-1015 to induce enhanced anti-tumor effects with lower systemic toxicity compared to CTLA-4 monotherapy." (PMID 30400822, 2018). "Rudqvist NP, Pilones KA, Lhuillier C, Wennerberg E, Sidhom JW, Emerson RO, Robins HS, Schneck J, Formenti SC, Demaria S. Radiotherapy and CTLA-4 blockade shape the TCR repertoire of tumor-infiltrating T cells." (PMID 30400822, 2018). "Tumor bearing mice were administered anti-CTLA-4, anti-PD-1, anti-PD-L1, anti-OX40 or anti- LAG3 twice weekly for 3 weeks." (PMID 30400822, 2018). "The immunotherapeutic sensitivities in response to systemic CTLA-4 and PD-1 blockade therapies were determined by tumor growth kinetics and survival." (PMID 30400822, 2018). "Research has shown that HDACis can upregulate the expression of CD80 and CD86, hence improving tumor cell immunogenicity, promoting the elimination of tumor cells, and enhancing the treatment efficacy of antibodies targeting CTLA-4." (PMID 30558227, 2018). "Targeting with CTLA-4 or PD-1 or PD-L1 reverses the exhaustion of cytotoxic T lymphocytes thus leading to the elimination of tumor cells via the re-induction of the “natural” function of the T cell population." (PMID 29098404, 2018). "Immune checkpoint inhibitors cannot function unless its target receptors (PD-1, CTLA-4) exist in the tumor microenvironment." (PMID 29692957, 2018). "Here we sought to determine the contribution of Treg cell depletion to the in vivo anti-tumor activity of anti-CTLA-4 antibodies in the context of human FcγRs and human IgG isotypes." (PMID 29576375, 2018). "In the context of tumor-specific T cell immune responses, CTLA-4 is understood to negatively regulate T cell priming events in secondary lymphoid tissues, leading to an unresponsive, anergic or apoptotic phenotype." (PMID 29617360, 2018). "CTLA-4 is also highly expressed on regulatory T cells, and antibodies targeting CTLA-4 have been suggested to deplete them from the tumor microenvironment through Fc effector functions." (PMID 30627131, 2018). "Mice were subcutaneously implanted with MC38, B16F10 or MT4 cancer cells and treated with combined PLX4786 and anti-CTLA-4 or anti-PD-1 to determine the effects on tumor growth and on subpopulations of immune cells within the tumor microenvironment." (PMID 30400835, 2018). "The effects of siRNAs on the mRNA of IFN-γ, PD-1, PD-L1, CTLA-4 and Survivin in the tumor, liver and spleen were determined using quantitative RT-PCR." (PMID 30564277, 2018). "A high CTLA-4 positive lymphocyte density, however, was significantly correlated with a good prognosis only when tumor CTLA-4 expression was low." (PMID 29672601, 2018). "Flow cytometry was used to investigate surface CTLA4 expression on murine and patient T cell subsets, including tumor-infiltrating lymphocytes and T cells from matched patient blood." (PMID 30400822, 2018). "It has been pointed that PD1 or CTLA4 can inhibit the function of T cells in the tumor microenvironment." (PMID 29568411, 2018). "T cells are more likely to be primed for activation in the thymus as a result of CTLA-4 blockade, but their cytotoxic activity still relies on tumor MHC-I expression." (PMID 30497521, 2018). "The combination of a MEK inhibitor, anti PD-L1 and anti CTLA-4 improves survival in epithelial KP tumor models of NSCLC." (PMID 30400835, 2018).
tumor (continued). "In preclinical mouse models, surrogate anti-CTLA-4 antagonist antibodies have shown compelling anti-tumor efficacy." (PMID 29617360, 2018). "In cancer, tumor cells and immune cells often overexpress co-inhibitory molecules, such as PD-1/PD-L1 and CTLA-4, which suppress anti-tumor immunity." (PMID 30568653, 2018). "While both anti-PD1 and CTLA4 treatments showed certain degrees of success in reducing tumor growth, we demonstrated that in a pre-treatment setting, HDAC6i improves anti-tumor responses when combined with anti-PD1." (PMID 30400822, 2018). "The immune phenotypes of the patients’ tumor milieu demonstrated overexpression of multiple checkpoint blockade markers including PD-L1 (6.9%), PD-L2 (10.9%), CTLA4 (3%), LAG-3 (8.9%), TIM-3 (9.9%) and VISTA (15.8%)." (PMID 30400835, 2018). "Targeting PD-L1 enhanced the effectiveness of whole tumor cell vaccination when combined with CTLA-4 blockade." (PMID 29377881, 2018). "It is widely anticipated that the ongoing trials will provide formidable evidence to support clinical applications of PD-1/PD-L1 plus CTLA-4 checkpoint inhibitor combination regimens for patients with a substantial variety of tumor histologies." (PMID 29769148, 2018). "OncoVEXmGM-CSF in combination with an anti-CTLA-4 antibody led to complete SC tumor regression in 60% of mice." (PMID 30400822, 2018). "In cohort 2, 49 patients received 1 mg/kg nivolumab plus ipilimumab, which is an anti-cytotoxic T lymphocyte-associated protein 4 (CTLA4) monoclonal antibody, at a dosage of 3 mg/kg every three weeks; 24% of the tumor samples were PD-L1 positive." (PMID 30365605, 2018). "a-CTLA4-TGFβRIIecd is more effective in reducing tumor-infiltrating Tregs and inhibiting tumor progression compared with CTLA-4 antibody (Ipilimumab)." (PMID 29467463, 2018). "In germ-free or antibiotic treated mouse models, CTLA-4 blockade was ineffective at preventing tumor progression." (PMID 29368638, 2018). "The authors develop bifunctional proteins comprising CTLA-4 or PD-L1 immune checkpoint-targeted antibodies fused to a “TGFβ trap” and show that they counteract tumor immune tolerance and enhance the efficacy of these antibodies." (PMID 29467463, 2018). "Combination CSF1/CSF1R and PD-1 or CTLA-4 blockade synergistically restrained tumor progression, compared to controls." (PMID 30294755, 2018). "Conjugation of an anti–CTLA-4 aptamer to a STAT3 siRNA helped to overcome this limitation and achieved STAT3 gene silencing in both tumor-associated T cells and tumor cells." (PMID 29865257, 2018). "More recently, a number of antibodies targeting cellular immune checkpoints (e.g. PD-1/PD-L1 and CTLA-4) have been developed to promote the activation of T cells and subsequent tumour control." (PMID 29875199, 2018). "CTLA-4 blockade plus Id2kd vaccination induces tumor specific T-cell expansion and tumor infiltration in mice, in which the infiltrating CD8 T cells are characterized by PD1 expression." (PMID 29377881, 2018). "The combined treatment groups of PLX7486 and anti-CTLA-4 or anti-PD-1 showed significant superiority in vivo in multiple tumor models." (PMID 30400835, 2018). "The latest findings in an animal model show that CD8+ T cells play an essential role in anti-CD20-mediated tumor regression but the blockade of regulatory T cells by CTLA-4 can synergize with anti-CD20." (PMID 30713498, 2018). "ATOR-1015 is a next generation CTLA-4 antibody with tumor-directed activity for enhanced efficacy and reduced toxicity." (PMID 30400822, 2018). "Experimental studies have shown that anti-programmed cell death protein 1 (PD1) and anti-cytotoxic T lymphocyte-associated antigen 4 (CTLA4) synergizes with anti-CXCR2 or anti-Ly6G, respectively, to delay tumour growth." (PMID 30304046, 2018). "One study of patients treated with CTLA-4 mAb showed that a high baseline expression of Foxp3+ Treg cells in the tumor was correlated with better clinical outcomes." (PMID 29482595, 2018).